CFAP58-DT (CFAP58 divergent transcript)
Synonyms: lncITPRIP-1; CCDC147-AS1; CFAP58-AS1
Gene: Long non-coding RNA gene on chromosome 10 (104,351,296 to 104,353,685, reverse strand). Ensembl gene ENSG00000231233.
Diseases named in the same sentence as CFAP58-DT in open-access papers:
CFAP58-DT is named in the same sentence as 1 disease in open-access papers, as found by Europe PMC text mining. Sharing a sentence is not in itself a finding about the gene and the disease.
CFAP58-DT shares sentences with these, for which no sentence is quoted: viral infection (1 paper).